RNU6-572P (RNA, U6 small nuclear 572, pseudogene)
Gene: Small nuclear RNA gene on chromosome 5 (139,221,758 to 139,221,837, forward strand). Ensembl gene ENSG00000252533.
Homologues: Orthologues: chimpanzee U6 (100% identical), rabbit U6 (85% identical), rabbit U6 (72% identical). Paralogues in human: RNU6-921P (92% identical), RNU6-10P (91% identical), RNU6-15P (90% identical), RNU6-16P (90% identical), RNU6-17P (90% identical), RNU6-18P (90% identical), RNU6-393P (90% identical), RNU6-41P (90% identical), RNU6-44P (90% identical), RNU6-1 (89% identical), RNU6-1060P (89% identical), RNU6-1075P (89% identical), and 1283 more.